CCR2 (C-C motif chemokine receptor 2)
Diseases named in the same sentence as CCR2 in open-access papers (continued):
Sharing a sentence is not in itself a finding about the gene and the disease.
tumor (continued). "Dual targeting of the CCR2+ TAMs and CXCR2+ TANs improved the anti-tumor immunity in pancreatic adenocarcinoma." (PMID 35585567, 2022). "As a major attractant of BM-derived cells that contribute to the creation of a tumor-supportive TME, the CCL2/CCR2 axis is of clinical relevance (discussed under ‘Modulating the immune TME’)." (PMID 36568151, 2022). "Therapeutics that disrupt the CCR2/CCL2 axis have been effective in blocking macrophage infiltration and reducing tumor growth and metastasis in preclinical models of cancer, with variable activity demonstrated in early phase clinical trials." (PMID 33603130, 2022). "ACKR2–/– mice have been demonstrated to have increased killing activity of NK cells through enhanced CCR2 expression and NK infiltration into the CCL2-expressing melanoma tumor microenvironment." (PMID 35677043, 2022). "Next, we clarified the role of CCR2 and CXCR2 antagonists in the TACE-induced inhibition of tumor growth." (PMID 36403057, 2022). "When the production of reactive nitrogen species is inhibited, the CCL2/CCR2 pathway is working to allow CD8 T-cell recruitment and tumor growth control." (PMID 36429101, 2022). "Once in these areas, the hypoxic conditions cause downregulation of the receptors for several of these factors, such as CCR2 and CCR5, contributing to the retention and entrapment of TAMs in the tumour." (PMID 36497148, 2022). "For example, antagonists to CXCR4, CCR2, CCR5, and CXCR1/2 were developed to disrupt tumor invasiveness, but now have been observed to influence immune cell migration in the TME." (PMID 33603130, 2022). "Among them, immune-related genes such as CCL2, CCR2, CXCR4, and CCR5 play a role in the recruitment of TAMs in tumor development and progression." (PMID 35874816, 2022). "Blockade of CCL2/CCR2 and CXCLs/CXCR2 enhanced the anti-tumor effect of TACE treatment in this model." (PMID 36403057, 2022). "Similarly, we hypothesized that the chemokines CCL2 and CCL5—which are pro-metastatic chemokines that promote tumor cell invasion and act mainly through the Gαi-signaling receptors CCR2 and CCR5, respectively —also contribute to increased invasion of WT-PD-L1-MDA cells." (PMID 35205789, 2022). "We used the 4PD nanoparticle for the in vivo targeted silencing of CCR1, CCR2, CCR5, and/or CCR7 in the myeloid cells of tumor bearing mice to evaluate the effect of treatments on tumor growth, myeloid cell trafficking and polarization." (PMID 35064009, 2022). "CyTOF analysis of these tumors revealed that the CCR2+ admixed tumors had significantly fewer CD11b+ myeloid cells and significantly increased CD8+ T-cells present within the tumor." (PMID 35140221, 2022). "There is extensive evidence to indicate that the CCL2/CCR2 and CXCLs/CXCR2 axes can stimulate tumor growth and angiogenesis, and promote the infiltration and activation of host immune cells." (PMID 36403057, 2022). "The anti-tumor effects of blocking the CCL2/CCR2 and CXCLs/CXCR2 axes by CCR2 and CXCR2 antagonists in combination with TACE were evaluated in HCC rats." (PMID 36403057, 2022). "Whereas the enrichment of CCR2+ macrophages has been observed in PDAC after radiotherapy, neutralizing or genetic depletion of CCL2 improves radiotherapy responses and attenuates tumor growth in mouse models." (PMID 36230914, 2022). "In these models of metastasis, once the tumor cells arrive, there is an immediate CCL2-mediated recruitment of CCR2-expressing classical monocytes that promote metastasis seeding and establishment." (PMID 36077870, 2022). "Monocytes are recruited around tumor tissue and differentiated into macrophages through the combination of CCR2 on its surface and chemokine CCL2 (synthesized by tumor cells or other cells), which together form TME with other components." (PMID 36611857, 2022). "A CCR2 inhibitor (PF-04136309) reduced TAM infiltration and tumor growth in a syngeneic PDA tumor mouse model." (PMID 33603130, 2022).
tumor (continued). "CCL2 secreted by oncogene-induced senescent hepatocytes can recruit CCR2+ immature myeloid cells and then inhibit the antitumor function of NK cells, thereby promoting HCC tumor growth." (PMID 35281057, 2022). "After binding to CCR2, it induces tumor cells to metastasize to the bone through TAM-mediated tumor angiogenesis." (PMID 36072582, 2022). "Taken together, these results suggest that bone marrow-derived CCR2+/CX3CR1+ cells from naïve and tumor-bearing animals migrate to CCL2 and CCL7, in a CCR2-dependent manner." (PMID 36685592, 2022). "Inflammatory monocyte mobilization decreases patient survival, and targeting the CCL2/CCR2 or CSF1/CSF1R axis that allows targeting macrophages or myeloid cell lineages improves chemotherapeutic efficacy and anti-tumour T-cell response." (PMID 36077801, 2022). "Mechanistically, PADC cells elevate the production of CCL2 chemokine to attract CCR2+ M2-like macrophage infiltration, which reciprocally provides tumor cells with abundant TGFβ to promote KRAS-independent tumor growth." (PMID 36230914, 2022). "In the clinical trials of FOLFIRINOX with CCR2 antagonists PF-04136309 and CCX872, respectively, better local tumor control rate was observed (NCT01413022), and the overall survival rate was also improved compared with chemotherapy alone (NCT02345408)." (PMID 36699061, 2022). "To assess whether the tumor-associated inflammatory monocytes (TAIMs) could internalize BG34-200-AF647 after IV administration, we examined the frequency of BG34-200-AF647+ cells in the circulating CD11b+CCR2+ cells and found that more than 30% cells were CD11b+CCR2+BG34-200-AF647+." (PMID 36497393, 2022). "In irradiated MC38 and LLC tumor models, IFN-β can induce mCCL12 expression by activating the stimulator of interferon genes (STING) pathway, which in turn mobilizes CCR2+ Mo-MDSCs into tumors, leading to radioresistance." (PMID 35281057, 2022). "BMS-813160 is a small-molecule inhibitor that antagonizes both CCR2 and CCR5 and is currently under investigation in combination with nivolumab for the treatment of a variety of tumor types (NCT03496662, NCT03767582, NCT03184870, NCT04123379, and NCT02996110)." (PMID 36031601, 2022). "In the HPA database, protein expressions of the seven genes (ADAMTS8, CCR2, CYSLTR2, FAM129C, FCER1A, GAPT, PKHD1L1, and ZNF831) were markedly low in tumor tissues with less intense antibody staining and fewer stained cells in LUAD." (PMID 36033829, 2022). "qRT-PCR analysis of CD11b+cells from the tumor or the spleen of 4T1 bearing mice indicates that CCR1, 5 and 7 are significantly upregulated at the tumor whereas CCR2 is highly expressed on myeloid cells from both tissues." (PMID 35064009, 2022). "Multiple preclinical murine models have demonstrated the potent efficacy of CCR2 inhibitors and anti-CCL2 antibodies in reducing tumor growth and metastasis." (PMID 36679900, 2022). "This demonstrated that CCR2 is requisite for the WGP-driven influx of trained innate immune cells into the pancreas and that those are consequential for the anti-tumor effects." (PMID 35140221, 2022). "Conversely, other immune cells, such as the M2 type of macrophages, express C-C motif chemokine receptor 2 (CCR2, receptor of CCL2), and which is an irreplaceable factor that promotes tumor metastasis." (PMID 35252165, 2022). "This possibility is highly supported by the fact that joint inhibition of CXCR1/2, CCR2 and CCR5 led to complete inhibition of tumor cell invasion and of CCL2 and CCL5 production." (PMID 35205789, 2022). "It is also worth investigating which ligands CCL8 binds to, including CCR1, CCR2, CCR3, and CCR5, and thus how it affects the downstream signaling pathways that lead to changes in the biological behavior of tumor cells." (PMID 36072582, 2022). "Once the capacity of 4PD to bind and transfect myeloid cells in vivo with multiple shRNAs was determined, we evaluated the effect of chronic CCR1, CCR2, CCR5, and CCR7 silencing on tumor progression." (PMID 35064009, 2022).
tumor (continued). "Chemokine MCP-5 (CCL12) facilitates tumor metastasis and blockade of CCL2/CCR2 axis enhances CD8+ T cell-mediated antitumor immunity." (PMID 35935577, 2022). "Our results show that treatment with CCR2 and CXCR2 antagonists improves the effect of TACE to provide increased anti-tumor activity." (PMID 36403057, 2022). "In the tumor-infiltrating CD45.1+ cells, some CD11b+F4/80+CCR2+Ly6C+ monocyte-derived macrophages expressed CD169." (PMID 36266311, 2022). "By addressing specific chemokine receptors that signal via Gαi and mediate tumor cell invasion, we demonstrated that the intrinsic activities of PD-L1 were mediated by the chemokine receptors CXCR1/2, CCR2 and CCR5." (PMID 35205789, 2022). "The combined CCR2 plus CXCR2 blockade enhanced the chemotherapeutic efficacy and improved the survival of tumor-bearing mice." (PMID 35664746, 2022). "A variety of chemokine/chemokine receptor strategies have been utilised in immunotherapeutic T cell preclinical work to facilitate CAR T cell targeting to tumour masses, including the exploiting the CXCR3, CXCR2, CCR5, CCR2, and CCR3 axes." (PMID 35205725, 2022). "Inhibitor of FROUNT, a coactivator for CCR2 and CCR5 signals, showed an inhibitory effect on E0771 tumor growth by blocking TAM infiltration." (PMID 35835809, 2022). "CCR2 has been reported to serve as the primary functional receptor for CCL2 in the TME, and the CCL2/CCR2 axis is known to play a crucial role in tumor progression." (PMID 34874922, 2022). "The SBRT + αPD-1 + CCR2/5i treatment group demonstrated significantly better local tumor control, better metastasis control, and improved survival in this model vs. any other treatment group including the SBRT + αPD-1 and SBRT + CCR2/5i treatment groups." (PMID 35404390, 2022). "Neutralization of the MCP-1/CCR2/CCR4 axis by knocking out CCR2/CCR4 recapitulates tumor growth and tumor landscape, as observed following pharmacological inhibition of MCP-1." (PMID 35980743, 2022). "PYK2 modulates key signaling pathways mediated by CCL2/CCR2, CXCR4, and IL‐4Rα/pSTAT6, and positively regulates macrophage recruitment and polarization, tumor angiogenesis, and tumor growth." (PMID 35092356, 2022). "Another study showed that the blockade of CCL2 binding to its receptor CCR2 on macrophages or depletion of CCL2 decreased monocyte recruitment and prolonged tumor survival in mice." (PMID 35740975, 2022). "CCR2 and its cognate ligand MCP-1 have been extensively studied for their roles in the tumor microenvironment." (PMID 35551672, 2022). "CSF-1 has been described as the most important tumor-derived factor leading to monocyte recruitment through CCL2/CCR2 interaction, so CCR2 blockade therapies have been effective in suppressing TAM recruitment." (PMID 34209703, 2021). "By interacting with CCR2, CCL2 promotes cancer cell migration and recruits immunosuppressive cells to the tumour microenvironment, favouring cancer development." (PMID 34464477, 2021). "In the tumor microenvironment, the interaction between CCL2 and C-C motif chemokine receptor 2 (CCR2) regulates the chemotaxis of TAMs and contributes to cancer progression." (PMID 33891564, 2021). "For example, the blockade of CSF1/CSF1R pathway and CCL2/CCR2 axis prevented TAM recruitment and improved anti-tumor immunity." (PMID 34575463, 2021). "It targets upregulation of CCL-2/CCR-2 and CXC3CL-1/CX3CR-1 axis in macrophage-tumour cell crosstalk." (PMID 34336101, 2021). "In vivo studies in Lewis lung carcinoma (LLC) mouse model studies using genetic ablation of monocyte recruitment markers CCR2 and CX3CR1 and macrophage depletion using clodronate also have shown inhibited tumor growth and metastasis." (PMID 34439281, 2021). "The CCR2 and its ligand CCL2 signaling axis are involved in cancer pathogenesis by recruiting immune cells to tumor sites, thereby mediating various immune responses." (PMID 33949150, 2021).
tumor (continued). "Several pre-clinical studies have demonstrated that targeting TAMs via the CCL2-CCR2 pathway, with CCR2 antagonists or CCL2 neutralizing antibodies, increases the survival of tumor-bearing mice." (PMID 34572939, 2021). "Especially, MCP-1/CCR2 and IL-8/CXCR signaling is known to induce EMT in various cancer cell lines, which are considered to be potential targets of tumor progression and metastasis." (PMID 34294770, 2021). "A preclinical study reported a dual targeted strategy, where CCR2 inhibition combined with CXCR2 blockade resulted in notable tumour suppression and improved survival in tumour‐bearing mice." (PMID 34464477, 2021). "To confirm the pivotal role of CCL2-CCR2 signaling in the communication between tumor cells and macrophages, we evaluated CCL2, CCR2, and CCR4 expression in the tumor." (PMID 34580284, 2021). "Inhibition of CCL2/CCR2 or CSF1/CSF1R signaling pathway can reduce the intratumoral infiltration of M2-TAM and inhibit tumor growth and metastasis." (PMID 34583750, 2021). "In response to treatment with a CCR2 antagonist, which inhibits MonoMac infiltration into the PDAC TME, there is a corresponding increase in neutrophil infiltration into the tumor." (PMID 35008355, 2021). "Altogether, CCL2 and its receptor CCR2 are upregulated in tumours and engaged in tumour metastasis through the induction of EMT, the promotion of tumour cell extravasation and the establishment of a PMN." (PMID 34464477, 2021). "CCR2 inhibitors and anti-CCL2 antibodies (CNTO 888) have demonstrated efficacy in reducing tumor growth and metastasis in several pre-clinical murine models." (PMID 34094963, 2021). "Results of the present study are consistent with findings from previous studies which indicated that high expression of CCR2 and CCR5 promotes tumor progression." (PMID 34745969, 2021). "On the contrary, several sets of chemokines and their receptors, such as CCR2/CCL2, CXCR2/CXCL5, and VEGF, have been reported to promote tumor progression in other tumors by enhancing immunosuppressive M2-TAM and MDSC function." (PMID 34200100, 2021). "The chemokine (C-C motif) ligand 2 (CCL2)/chemokine (C-C motif) receptor 2 (CCR2) axis drives chemoresistance and immunosuppressive mechanisms in the tumor microenvironment." (PMID 34358103, 2021). "Furthermore, analysis of 366 HCC tumor samples from TCGA demonstrated positive associations of tissue CRP level and genes related to myeloid cells, including CD68 and CD14, as well as chemokines and receptors for the chemotaxis of monocytes or neutrophils, such as CCL2, CCR2, and CXCL1." (PMID 35070979, 2021). "In the tumor microenvironment, CCL2 interacted with CCR2 on the surface of macrophages to mediate the chemotaxis of monocytes and TAM to facilitate cancer progression." (PMID 33891564, 2021). "MDSCs and precursor myeloid cells express CCR2, a receptor for CCL2, which is a prevalent chemoattractant in MDSCs recruitment to the tumor." (PMID 34065010, 2021). "The number of tumours was dramatically decreased by the administration of etanercept, a specific TNF-α antagonist, or propagermanium, a CCR2 antagonist, even when given after treatment with AOM and DSS13,58." (PMID 34620946, 2021). "Previous studies have reported that CCL7 can combine with CCR2 to activate the STAT3 signal pathway and thus promote tumor cell metastasis." (PMID 33986252, 2021). "Further, dual targeting of CCR2+ TAMs and CXCR2+ TANs restored anti‐tumour immunity and improved the chemotherapeutic effect, providing the theoretical basis for targeting both CCR2 and CXCR2 in future clinical trials." (PMID 34464477, 2021). "Mouse models have demonstrated that CCR2/CCR5 inhibition can effectively restrict TAM infiltration, providing a more favorable anti-tumor balance within the TME." (PMID 34771675, 2021).
tumor (continued). "For example, in models of breast cancer, CCR2+ monocytes are the main source of TAMs, accounting for approximately 40% of all CD45+ cells within tumor tissues, compared to less than 10% derived from TRMs." (PMID 34178692, 2021). "Cancer cells and stroma can also secret chemokine ligand 2 (CCL-2) to recruit C-C chemokine receptor type 2 (CCR2+) monocytes in metastatic lesion, facilitating tumor seeding." (PMID 34063848, 2021). "Inhibitors of CSF1R, CCL2 and CCR2, CD47/SIRPα complex antagonists, CD40 agonist antibodies, and inhibitors of PI3Kγ and TREM2 protein are undergoing clinical evaluation for various tumor types." (PMID 34638378, 2021). "Interaction between CCR2 on monocytes with its ligand (CCL2) induces migration of monocytes from the circulation to the tumor tissue and promotes tumor proliferation." (PMID 34445615, 2021). "Novel strategies, such as the transfection of tumor migratory chemokines and their receptors, CXCL11 and CCR2, have been utilized to enhance the tumor localization of CAR-T cells with significant success." (PMID 33918403, 2021). "To further investigate the interaction of the four factors, we analyzed the expression levels of BTK, CCR2 and SCLM4 in KLRG1 knockdown A549 tumor cells." (PMID 34187403, 2021). "To further determine the role of CCL2/CCR2 signaling on EE-mediated antitumor immunity, we investigated tumor-infiltrated immune cells in DEN/CCl4-induced tumor by flow cytometry analysis." (PMID 34593796, 2021). "CCR2/CCL2 signaling is responsible for the infiltration of both TAMs and Tregs, which often promote immunosuppressive functions facilitating tumor growth." (PMID 34203660, 2021). "Conceivably, local depletion of CCR2+ TAM, Treg and tumor cells as well as local neutralization of ligand CCL2 in TME will likely enhance anti-tumor arm of immunity." (PMID 34804061, 2021). "A combined blockage of CCR2 and CXCR2 in a murine PDAC model prevented both CCR2+ macrophages and CXCR2+ neutrophils from entering the tumor, which led to an improved anti-tumor immunity and response to chemotherapy." (PMID 34203869, 2021). "Whereas the use of an anti-CCL2 monoclonal antibody reduced both the growth of primary malignant lesions and the metastases number in an implantable tumor model, CCL2 or CCR2 knockout mice developed transgenic tumors and had an increased number of metastases." (PMID 33540898, 2021). "CAFs were able to recruit CCR2+ monocytic cells and polarize such cells into MDSCs, which hampered CD8+ T-cell-dependent tumor immunity." (PMID 34386431, 2021). "Additionally, MCP-1 expression levels in the TME are positively correlated with increased stromal cell and TAM CC chemokine receptor 2 (CCR2) expression, associated with tumor invasion depth, lymph node metastasis, and distant metastasis, and predict poor prognosis in patients with ESCC." (PMID 33995371, 2021). "Monocytic-MDSCs express CCR2 and CCR1/CCR5, and can be recruited into tumor tissues by CC chemokines such as CCL2 and CCL5, respectively." (PMID 34885241, 2021). "As for the CCR2 axis, the CCR5 axis is not only related to Treg recruitment, because its ligands (CCL3, CCL4, CCL5 and CCL8) are also involved in tumor progression and metastases." (PMID 33924428, 2021). "Three components of this proof of mechanism are the depletion of TAM from the tumor, a decrease of CD14 + CCR2+ IM in the peripheral blood, and the accumulation of CD14 + CCR2+ IM in bone marrow." (PMID 31297636, 2020). "The chemokine receptors CCR2 and CCR5 are major chemotactic regulators of tumor-promoting macrophages at the tumor site, and blockade of these receptors impair tumor progression in experimental animal models." (PMID 32001710, 2020). "It is conceivable that the CCR2 and CCR5 axes are also involved, together with other axes in step III of homing to the tumor site." (PMID 33193327, 2020).